CD4 (CD4 molecule)
Diseases named in the same sentence as CD4 in open-access papers (continued):
Sharing a sentence is not in itself a finding about the gene and the disease.
viral infection (continued). "Healthy people, after taking two herbal formulas (SJY and Yu Ping Feng San), have a short-term increase in their CD4/CD8 ratio, so herbal formulas can prevent viral infections, including SARS." (PMID 34200223, 2021). "In the context of viral infections, the PD-1 upregulation on HIV-specific CD4+ T cells correlates with viremia and has been shown to be important for regulating cytokine secretion." (PMID 33567792, 2021). "CD4+CD8+ double-positive T (DPT) cells have been discovered in recent years to play an important role in autoimmune diseases and viral infections, but the frequency and significance of DPT in primary Sjogren's syndrome are still unclear." (PMID 34095321, 2021). "In CD4+ myeloid lineage and resting T-cells, SAMHD1 blocks HIV-1 and other viral infections by depletion of the dNTP pool to a level that cannot support replication." (PMID 32576829, 2020). "Our data demonstrate that CD4+ and CD8+ T cells can be directly regulated by type III IFNs to combat viral infections." (PMID 32353085, 2020). "Tec kinase signaling pathway is also required for differentiation and development of CD4+ and CD8+ T cell, and CD8+ T cell activation in response to viral infection." (PMID 32859030, 2020). "Cellular immune responses, consisting of both CD4+ T and CD8+ T cells, are essential for the control of viral infection." (PMID 32641700, 2020). "It has been shown that the viral vaccines are able to induce a cellular immune response, including CD4 and CD8 lymphocytes, against viral infections." (PMID 32545330, 2020). "It is known that during acute viral infections, IFN-Is exert their activity directly on B cells or by stimulating B cell responses through DCs or CD4+ T cells resulting in B cell activation, production of neutralizing antibodies and isotype class switching." (PMID 33391269, 2020). "FACS analysis of CD3+CD4+ and CD3+CD8+ cell population after 24 h of virus infection revealed that H5N1 HPAI induced the depletion of both populations." (PMID 33614753, 2020). "NK cells regulate CD4+ and CD8+ T cells in acute viral infection, vaccination, and the tumor microenvironment." (PMID 32733814, 2020). "Next, since both CD4+ and CD8+ T cells are crucial to protect against viral infection, including FMDV, we evaluated T cell subtypes induced by VLPFMDV vaccination formulated with DDA and MPL." (PMID 33142799, 2020). "Here we directly examined the effect of C15 on CD4+ and CD8+ T cell activation both in the context of viral infection and expression of C15 in isolation." (PMID 32745153, 2020). "In mammals, depletion of CD4+CD25+ cells by anti-CD25 antibody during bacterial and viral infections relieves the suppression of Treg and improves bacterial and viral clearance." (PMID 33022909, 2020). "Lymphocyte subsets, namely CD4+ T cells, CD8+ T cells, B cells, and NK cells are primarily involved in the humoral and cytotoxic immunity against viral infection." (PMID 33261583, 2020). "In particular, the authors focused on lncRNAs that were upregulated upon viral infection, and found that LINC02574-201 or HIV-1 enhanced lncRNA (HEAL) was significantly elevated upon infection in both MDMs and in primary CD4+ T cells." (PMID 32183241, 2020). "HLA restricted CD4+ and CD8+ T cells are activated upon viral infection and several epitopes have been identified." (PMID 33072068, 2020). "In many chronic viral infections, including TMEV, FoxP3+CD4+ T cells appear to contribute to the pathogenesis by inhibiting protective T cell functions and consequently promoting viral persistence." (PMID 33086489, 2020). "Previous studies on SARS-COV and MERS-COV showed that T cells, particularly CD4+ and CD8+ T cells, played a crucial role in inhibiting or weakening overactive innate immune responses during viral infection." (PMID 32641174, 2020). "Accumulation of damaged DNA and apoptotic CD4 T cells indicates an impairment of the TCR signaling and DNA damage repair machinery during viral infection." (PMID 33643305, 2020).
viral infection (continued). "In contrast, under low viral infection (2 × 105 PFU), the high initial virus-specific CD4+ T cells played a protective role in the development of clinical signs compared to the mice that received normal SJL CD4+ T cells." (PMID 33086489, 2020). "In contrast to the mice depleted with anti-CD4+ T cell antibodies, when CD4−/− mice were infected with MCMV, these mice were able to clear viral infection in all organs, albeit at a slower rate (of 200 to 400 days post-infection) than wildtype controls." (PMID 32509591, 2020). "In acute viral infection for instance, after the clearance of LCMV in mice, virus-specific CD4+ T cells that survived the contraction phase can be maintained for 60–150 days." (PMID 30828337, 2019). "Our experiments indicate that miR-155 in CD4+ T cells controls their activation, proliferation, and cytokine production in vitro and in vivo upon immunization with OVA as well as during VSV viral infection." (PMID 31275315, 2019). "However, also CD4+ T cells are important in anti-viral defense and therefore we were interested whether miR-155 was involved in the CD4+ T cell mediated response to viral infection." (PMID 31275315, 2019). "Taken together, these data suggest that during viral infection, proper APC-T cell interactions are crucial for the generation of virus specific CD4+ T cell responses and that altering this communication has dramatic consequences." (PMID 31275315, 2019). "During viral infections, MDSCs or MDSC-like cells suppress CD4+ and CD8+ T cells proliferation, migration, and function." (PMID 31139193, 2019). "Eight days after infection, 12% of the total CD4+ T cells in the spleen were CD45.2+, suggesting a robust expansion of WT OTII T cells after viral infection." (PMID 31275315, 2019). "The present study reports that in case of viral infection (BPIV-3 and BoHV-1), CD4, CD8, and IFN-γ gene expression levels were increased." (PMID 30823555, 2019). "Thus, arsenic trioxide may prevent the spread of viral infection to bystander CD4+ T cells." (PMID 31380187, 2019). "CD4 and CD8 T cells are an important part of the host’s capacity to defend itself against viral infections." (PMID 31382545, 2019). "The CD4/CD8 ratio is considered an indicator of immune system effectiveness, and it has been used to diagnosis and monitor viral infections, such as HIV and hepatitis." (PMID 31749792, 2019). "As anticipated, preclinical data suggests similar in vivo effects as IL-21 application has been shown to support CD4+ and CD8+ memory Tcell formation during amongst others viral infections." (PMID 29568345, 2018). "In addition, future work should determine whether long-lived CD4+ TSCM can be induced by vaccination, and whether they are associated with long-term memory responses and protection, as observed for CD8+ TSCM upon yellow fever vaccination as well as in adoptive immune-therapy." (PMID 29545791, 2018). "In acute viral infection, dendritic cells (DCs) initiate TFH programming by priming antigen-specific CD4+ T cells for activation." (PMID 29875775, 2018). "As a marker of central memory CD4+ T cells, L-selectin’s role in promoting HIV adhesion is consistent with TCM being the preferred target for the viral infection." (PMID 30026537, 2018). "Recently, the cytotoxic CD4+ T lymphocytes were identified in the human PBMC, mostly during chronic viral infections." (PMID 29850628, 2018). "IFN-γ is an important product of activated NK and effector CD4+ and CD8+ T cells, which are induced during viral infections." (PMID 29545920, 2018). "Recently, its role in innate and adaptive immunity has been demonstrated, through its involvement in regulation of CD4, CD8 and Treg after viral infection." (PMID 29447178, 2018). "Recent reports on LN-resident DCs (CD8+ cDC1) strongly advocate their role as a platform for CD4+ T cells in augmenting memory CD8+ T cell formation, recall and fitness in virus infection models." (PMID 30622538, 2018).
viral infection (continued). "Several studies have described CD4+ or CD8+ T cells as the critical source of IL-10 during protozoan and viral infection, contributing either to protection or to chronicity." (PMID 28584007, 2017). "In this study, we solved the crystal structure of a binary complex of HIV-1 gp120 and CD4, thus contributed to our understanding of the conformational rearrangements that HIV-1 gp120 undergoes during the course of virus infection." (PMID 28429756, 2017). "The identification of CD4 CTL both in healthy humans and directly ex vivo following viral infection raises the question of how these cells are generated in vivo." (PMID 28167943, 2017). "Viral infection sets in motion a cascade of immune responses, including both CXCR5+CD4+ T follicular helper (Tfh) cells that regulate humoral immunity and CCR5+CD4+ T cells that mediate cell-mediated immunity." (PMID 28553284, 2017). "The authors confirmed that viral infection increases the frequency of CRTAM+ cells in the lung and that CRTAM knock-out mice exhibit decreased CD4 CTL activity during infection." (PMID 28167943, 2017). "FN1 was also reportedly to facilitate viral infection through interaction with virus, such as HIV-1, in activated CD4+ T cells." (PMID 28591220, 2017). "It is known that viral infection induces antiviral immune response mediated by NK cells, CD8+ and CD4+ lymphocytes." (PMID 28289417, 2017). "Transcriptional profiling demonstrated that Egr2 and 3 are upstream regulators of genes required for expansion and suppression of effector differentiation in both CD4 and CD8 T cells in response to viral infection." (PMID 28487311, 2017). "Among the proliferation regulators, Egr2 and 3 directly control the expression of Myc in both CD4 and CD8 T cells in response to viral infection, which is a key transcription factor for T cell proliferation." (PMID 28487311, 2017). "Therefore, we assessed the differentiation of effector CD4 and CD8 T cells in response to viral infection by analysis of production of effector cytokines and granzyme B. We discovered that Egr2 and 3 promoted clonal expansion but profoundly suppressed differentiation of effector CD4 and 8 T cells." (PMID 28487311, 2017). "Both the magnitude and quality of antiviral CD4+ and CD8+ T cell responses are critical for the control of viral infection and the course of (symptomatic) illness." (PMID 29145441, 2017). "Coinciding with these findings, a microscopy-based study showed that in the course of viral infection, CD8+ T cells are activated after CD4+ T-cell contact with infected DC." (PMID 29147022, 2017). "In the context of a chronic viral infection, TNF induced CD4+ T cell dysfunction, also called T cell exhaustion, through PD-1 up-regulation." (PMID 29273790, 2017). "CD4 is the primary receptor for HIV, hence to protect CD4CAR expressing T cells from viral infection, we co-expressed the C46 fusion inhibitor in the CAR-containing vector (C46CD4CAR)." (PMID 29284044, 2017). "Whereas CD4+ cells have received much attention, CD8+ cells have mainly been studied as a potential link between autoimmunity and viral infections." (PMID 28635960, 2017). "Egr2 and 3 were essential to suppress Th1 differentiation in Th2 and Th17 conditions in vitro and also to control IFN-γ–producing CD4 and CD8 T cells in response to virus infection." (PMID 28455436, 2017). "Following DLI, a prompt increase in CD3 + CD4+ and CD3 + CD8+ counts was observed, with a concomitant reduction in viral load and a subsequent clearance of viral infections." (PMID 26768987, 2016). "Lower CD4/CD8 ratio can suggest chronic inflammation or perturbation in the immune system and is observed in conditions like viral infections and immune reconstitution inflammatory syndrome." (PMID 27942037, 2016). "Since then, several other studies have demonstrated the critical role of CD4+ T cells in both maintaining the functionality of cytotoxic CD8+ T cells and directly fighting the viral infection." (PMID 27895644, 2016).
viral infection (continued). "Here the authors use parabiosis and intravital microscopy to show that CD4+ memory T cells equilibrate with the circulation and cluster around hair follicles in response to CCL5-dependent responses to viral infection or contact sensitization." (PMID 27160938, 2016). "Following the DLI, a prompt increase in CD3 + CD4+ and CD3 + CD8+ counts was observed with a subsequent clearance of viral infections." (PMID 26768987, 2016). "Despite a trend of decreased viral loads compared to those in the primary viral infection during chronic SIV infection, viral loads persisted and depletion of CD4+ T cells was observed the gut mucosa." (PMID 27484833, 2016). "By contrast, in comparison to CD4+ T cells that express intermediate levels of CXCR5, a substantial increase of IFN-γ production by Tfh cells has been observed during viral infection." (PMID 31557986, 2016). "B cells appear to be required for optimal CD4 and CD8 T cell responses to acute and chronic viral infections in mice." (PMID 26042124, 2015). "The IFN-γ is a pleiotropic cytokine mainly secreted by CD4+ and CD8+ T cells and NK cells and has been believed to be a first line of host defense in the control of viral infections." (PMID 26783516, 2015). "The rapid carriage of nanoATV to sites of viral infection clearly demonstrates the potential for delivery of ART to viral reservoirs, thus delivering ART to CD4+T-cells in infected individuals." (PMID 26716700, 2015). "Observations on the alteration of exhausted CD4+ T cells in other viral diseases such as HCV and HIV support the theory that CD4+ T cells have important role in chronic viral infection." (PMID 25789969, 2015). "Although the rapid production of IFN-γ or granules by T cells is important in defense against virus infections, there seems to be few double IFN-γ+granzyme B+ or IFN-γ+perforin+ cells were visualized in each CD4+T-cell population analyzed." (PMID 25836633, 2015). "The lack of Tfh cells was not due to a failure to activate EGR2/3-deficient CD4 T cells because EGR2/3-deficient CD4 T cells did not have defects in activation marker expression, as indicated by CD44high cell frequency, or effector cytokine expression in response to viral infection." (PMID 25979336, 2015). "Fifty-one (34%) of the 149 immunocompromised travelers who were visiting yellow fever-endemic countries received the yellow fever vaccine; 29 (57%) of these travelers were HIV positive (83% of whom had a CD4 count > 500 cells/mm3)." (PMID 26304922, 2015). "One application is to examine the dynamics of CD4+ and CD8+ cells in the immune system during viral infection." (PMID 24842159, 2014). "The enrichment of virus-specific CD4+ and CD8+ T cells seems to be of great relevance for viral clearance and the long-lasting control of viral infections in a post-transplant setting." (PMID 25510656, 2014). "Although CD4+ T cells are essential for the generation of memory CD8+ T cells and sustained control of viral infections, their role in the initiation of the adaptive immune response to acute viral infection is controversial." (PMID 24466045, 2014). "HIV-infected CD4+ T cell migration has dire consequences in vivo, supporting HIV replication and dissemination of viral infection." (PMID 24551068, 2014). "We monitored the kinetics of the macrophages, neutrophils, CD4+T cell, CD8+ T cell, CD138+cell and CD38+cell in the lungs during the viral infection." (PMID 24666970, 2014). "To address the role of PGE2 in RT activity and viral DNA integration, we used a single virus infection cycle with HIV-1 VSV-Luc, which enters cells via endocytosis and thereby bypasses CD4/CXCR4 and the cortical actin." (PMID 24586238, 2014). "Previous studies with viral infections have shown that granzyme B is predominantly secreted by CD8+ T cells, although, the contributions of NK cells and CD4+ cytotoxic cells have also been suggested." (PMID 25471494, 2014).
viral infection (continued). "Recent studies highlighted an important role of NK cells in the regulation of CD4+ and CD8+ T cell subsets in various viral infections." (PMID 25506344, 2014). "Regulatory T cells (TR) are a subset of CD4 T cells that can suppress effector CD4 and CD8 T cells and have been shown to play an important role in a variety of viral infections." (PMID 24153060, 2013). "Both CD4+ and CD8+ CTLs are able to eliminate infected cells and are important for recovery from viral infection." (PMID 24470869, 2013). "The presence of human T cells in blood permit direct inoculations with HIV and direct monitoring of virus infection via blood plasma facilitating the longitudinal analysis of HIV infection and its effects on CD4+ T cells." (PMID 24156277, 2013). "In contrast, in a virus infection model with FV peak tetramer-positive CD8 T-cell, responses were far greater in magnitude than peak tetramer-positive CD4 T-cell responses." (PMID 22890822, 2013). "However, the molecular basis influencing the expression of cytotoxicity-related receptors on CD4+ T cells remain still under evaluation; however, it is though that chronic antigenic stimulation, such as occurring with some viral infections might lead to NKG2D expression." (PMID 23947399, 2013). "Additionally, there are potential confounders that may have affected the CD4 results including the difference in methods to determine CD4 counts, diurnal rhythms, physical and psychological stress, pregnancy, drug administration, tuberculosis, and viral infections." (PMID 22611485, 2012). "CD28 co-stimulation can affect the optimal development of secondary responses, proliferation of memory CD4+ and CD8+ T-cells and clearance of viral infections." (PMID 22253710, 2012). "Here we show that CD4+T cell responses specific for the ectodomain of DIII, were sufficient to afford partial protection against WNV virus infection." (PMID 21541326, 2011). "The fact that in our study WT virus infection induces extensive bystander apoptosis that is strikingly absent in V38E virus infection is evidence that the fusogenic activity of the Env glycoprotein may play a key role in bystander apoptosis and consequently CD4 decline in vivo." (PMID 21255440, 2011). "In order to investigate the role of RanBP2 in HIV-1 replication, we performed RNAi studies on Magi cells, a Hela cell line that expresses CD4, CCR5, and CXCR4 receptors, followed by the viral infection." (PMID 21179483, 2010). "In spite of the abundant evidence that cytotoxic CD8+ T lymphocytes (CTL) are the primary anti-HIV-1 effectors, a significant amount of information supports a protective role of specific CD4+ responses in HIV-1/SIV and other viral infections." (PMID 20552033, 2010). "In response to viral infection, Ag-specific CD8+ T cells express peak levels of STAT1 for a shorter period of time than CD4+ cells." (PMID 20436908, 2010). "Having established some characteristics of the studied cell population such as purity and permissiveness to productive viral infection, gene microarray analysis was performed to measure the impact of HIV-1 on host gene expression in CD4+ T lymphocytes." (PMID 19146679, 2009). "Our study showed that transient expression of the R88-A3G fusion protein in both Vif− and Vif+ HIV-1 producing cells drastically inhibited viral infection in HeLa-CD4-CCR5-cells, CD4+ C8166 T cells and human primary PBMCs." (PMID 18414671, 2008). "The proportion of CD4+ and CD8+ cells among CD69+ lymphocytes is shown 10 days after virus infection." (PMID 18335041, 2008). "These mice not only showed induction of a strong CD4+ and CD8+ T cell response following immunisation but also acquired strong resistance to virus infection." (PMID 18806877, 2008). "This has provoked our detailed assessment of the role of different subsets of DC in activating CD4+ and CD8+ T cells in viral infections." (PMID 18301768, 2008).